CYP11B2 (cytochrome P450 family 11 subfamily B member 2)
Diseases named in the same sentence as CYP11B2 in open-access papers (continued):
Sharing a sentence is not in itself a finding about the gene and the disease.
Hypertension (continued). "Aldosterone synthase is the key rate‐limiting enzyme in adrenal aldosterone production, and induction of its gene (CYP11B2) results in the progression of hypertension." (PMID 28904869, 2017). "Aldosterone synthase (CYP11B2) inhibition has emerged as a new option for the treatment of hypertension." (PMID 28352088, 2017). "In light of this, we propose that the differential response of variant CYP11B2, CYP11B1 and CYP17A1 genes to ACTH is an important determinant of blood pressure, tending to predispose individuals with an unfavourable genotype to hypertension." (PMID 28272372, 2017). "An alternative approach for the management of congestive heart failure and hypertension would be the inhibition of CYP11B2, probably leading to fewer adverse effects." (PMID 29312923, 2017). "In order to investigate the direct link between hypertension and diabetes mellitus, we here examined the effects of high glucose on CYP11B2 expression and aldosterone secretion using human adrenal H295R cells." (PMID 28904869, 2017). "This study provided candidates for novel drug-like CYP11B2 inhibitors by molecular simulation methods for the hypertension treatment." (PMID 27781210, 2016). "Altogether, we found nine genes (Cst3, Cyp11b2, Ephx2, Fn1, Igfbp2, P2rx4, Prkcd, RT1-Ba, and Sult1a1) annotated in the RGD as associated with hypertension in this group." (PMID 26822062, 2016). "CYP11B2 is regarded as promising target for the treatment of hypertension which has gained great attention." (PMID 27781210, 2016). "Glucocorticoid-Remediable Aldosteronism, a rare form of hypertension, is caused by a gene fusion between CYP11B1 and CYP11B2." (PMID 24658007, 2014). "The objective of the present study was to systemically examine the association between polymorphisms in the RAAS candidate genes (REN, AGT, ACE, AGTR, and CYP11B2) and hypertension." (PMID 24015270, 2013). "Another set of genes (CYPD6 and CYPD7) are involved in a gene conversion that causes debrisoquine polymorphism and a gene conversion between CYP11B2 and CYP11B1 has been linked to causing hypertension." (PMID 20148076, 2009). "LCI699 (Osilodrostat) was the first CYP11B2 inhibitor developed for use in PA and hypertension." (PMID 39170743, 2024). "Aldosterone gene CYP11B2 polymorphisms are associated with many diseases, such as Type 2 Diabetes Mellitus (T2DM), myocardial infarction (MI), left ventricular mass, hyperaldosteronism, arterial stiffness and hypertension." (PMID 37372364, 2023). "In essential hypertension, the aldosterone synthase gene (CYP11B2) plays a significant role." (PMID 37372364, 2023). "Taking EH as the dependent variable, multiple-factor logistic regression analysis was used to analyse the influence of the interactions between ACE, ACE2, CYP11B2 and noise on EH based on the multiplicative model after adjustment for BMI, family history of hypertension, TG, TC and other confounders." (PMID 35130889, 2022). "CYP11B2-inhibition could be an innovative strategy to treat illnesses accompanied by high aldosterone concentrations, such as drug-resistant hypertension, on the basis of primary hyperaldosteronism." (PMID 36293446, 2022). "Also, two loci, including rs62525059 (CYP11B2) and rs3774427 (CACNA1D), showed a suggestive association with resistant hypertension in variants previously associated with hypertension, the same as those previously associated with blood pressure." (PMID 34593835, 2021). "The unadjusted logistic regression analysis showed that age, sex, BMI and family history of hypertension were associated with complete clinical success, but adjusted CYP11B2 H-score and adjusted CYP11B1 H-score were not." (PMID 34631800, 2021). "Additionally, associations with CKD related pathologies, such as hypertension (GPX4, CYP11B2, ERCC4), cardiovascular disease, diabetes and cancer predisposition (ERCC2) were also observed." (PMID 31924810, 2020).
Hypertension (continued). "In addition, other genes were found to be associated with CKD related pathologies, such as hypertension (GPX4, CYP11B2, ERCC4), cancer predisposition (ERCC2), and cardiovascular disease (ERCC2)." (PMID 31924810, 2020). "GPX4, CYP11B2, and ERCC4 genes were associated with hypertension." (PMID 31924810, 2020). "In this article we have summarised evidence that common functional polymorphisms exist at the CYP11B1, CYP11B2 and CYP17A1 loci, and have hypothesised that each may predispose to hypertension." (PMID 28272372, 2017). "Compound 12 was a selective CYP11B2 inhibitor, which is the key enzyme for the production of aldosterone, which inhibition is a potential target for the treatment of congestive heart failure, myocardial fibrosis, and hypertension." (PMID 29312923, 2017). "Aldosterone synthase (CYP11B2) is the key enzyme for aldosterone biosynthesis and its inhibition is a promising approach for the treatment of congestive heart failure, cardiac fibrosis, and certain forms of hypertension." (PMID 29312923, 2017). "Recently, genetic analyses of KCNJ5, ATP1A1, ATP2B3, and CACNA1D have revealed that chronic overexpression of CYP11B2 induces not only aldosterone hypersecretion but also the formation of primary aldosteronism 8, resulting in the progression of severe hypertension." (PMID 28904869, 2017). "As our observation provides a novel insight into the etiology of hypertension in patients with diabetes, it may also lead to novel therapeutics, such as an inhibitor of CYP11B2 transcription, for patients with diabetes complicated with hypertension." (PMID 28904869, 2017). "Therefore, discovering the novel CYP11B2 inhibitors had become a new approach for treatment hypertension." (PMID 27781210, 2016). "Therefore, research and development of CYP11B2 inhibitor are regarded as a novel approach for the treatment of hypertension." (PMID 27781210, 2016). "Besides, CYP11B2 gene variations can also change the gene expression, therefore play an important role in many diseases, such as hypertension, primary aldosteronism and heart failure." (PMID 25102047, 2014). "Candidate gene studies of hypertension and BP have implicated several interactions between alcohol and genes [ADH2, ALDH2, SOD2, LEPR, ApoE, CYP11B2, NADH2, GNB3, and ADM]." (PMID 24376456, 2013). "Consistent with previous studies of patients with hypertension or dilated cardiomyopathy, we also found that the CYP11B2 −344CC genotype was over-represented among individuals with extreme elevation of aldosterone, defined as the 90th percentile for the study population." (PMID 23936266, 2013). "Meanwhile, it has been reported that the interaction of CYP11B2, angiotensin II type 1 receptors, and angiotensinogen could influence the development of renal insufficiency in essential hypertension." (PMID 23950878, 2013). "An amino acid polymorphism showing Lys173 rather than Arg173 in CYP11B2 gene has been associated with low-renin hypertension in Japanese populations." (PMID 19243623, 2009). "An adrenal steroid biosynthesis alteration via CYP11A and the 3β-HSD2, CYP21, CYP11B2 cascade is hypothesized to lead to increased aldosterone secretion, expanded plasma volume, and hypertension." (PMID 19662162, 2009). "Gene polymorphisms of the renin-angiotensin-aldosterone system (RAS), aldosterone synthase gene (CYP11B2), ATPase plasma membrane Ca2+ transporting 1 gene (ATP2B1), and endothelial nitric oxide gene polymorphisms have been studied and associated with an increased risk for hypertension." (PMID 39202743, 2024). "A number of RAAS gene polymorphisms, including those in the aldosterone synthase (CYP11B2), angiotensinogen (AGT), angiotensin II type 1 receptor (AT1R), and angiotensin-converting enzyme (ACE) genes, have been found to be strongly linked to hypertension and ischemic stroke." (PMID 37034069, 2023).
Hypertension (continued). "The main determinants of surgical cure in patients with primary aldosteronism were a duration of hypertension less than five years, number of antihypertensive medications ≤2, preoperative response to spironolactone, the presence of adenoma, and the TT genotype of the CYP11B2 gene." (PMID 32443509, 2020). "In addition to GRK4, gene polymorphisms related to the renin-angiotensin-aldosterone system (RAAS), such as angiotensin converting enzyme (ACE), angiotensinogen (AGT), angiotensin II type 1 receptor (AGTR1), and aldosterone synthase (CYP11B2), have been reported to be associated with hypertension." (PMID 22518293, 2012). "A previous study reported that haplo-insufficiency of Klotho in mice results in increased aldosterone synthase (CYP11B2) expression, elevated plasma aldosterone, and high blood pressure." (PMID 38573585, 2024). "Previous findings from animal studies have shown the impact of salt intake, hypertension, and proinflammatory cytokines on methylation and expression of the AGT and CYP11B2 gene." (PMID 36457109, 2022). "Aldosterone synthase (CYP11B2) and α-adducing (ADD1) are candidate genes that play key roles during essential hypertension (EH) incidence." (PMID 36035164, 2022). "In the abnormal β-catenin staining group, hypertension duration, aldosterone, ARR, cortisol, tumor diameter, tumor area, and CYP11B2 H-score were significantly higher than those of the wild-type group." (PMID 34631800, 2021). "Several genes responsible for rare Mendelian forms of hypertension have been identified (CYP11B1, CYP11B2, HSD11B1, MR, SCNN1B, SCNN1G, WNK1, WNK4) and shown to play a significant role in the renal control of BP." (PMID 19662162, 2009). "The difference of genotype frequencies among hypertension and normal groups were statistically significantat loci rs4425 (A/T) and rs4337 (G/C) in the ACE gene, at locus rs129876 (G/A) in the ATR gene and at locus rs1912 (C/T) in the CYP11B2 gene." (PMID 31484569, 2019). "Hence, since osilodrostat can also inhibit aldosterone synthase (CYP11B2), a reduction in blood pressure may be expected in patients with hypertension." (PMID 40429513, 2025). "The up-regulation of the Cyp11b2 gene found in the current study may result in aldosterone excess in the hypothalamus of ISIAH rats and may also contribute to the development of stress-sensitive hypertension." (PMID 26822062, 2016). "In addition, because most of the donors have died from acute illnesses which are known complications of hypertension, we cannot rule out that, in some subjects, a history of hypertension may have influenced the CYP11B2 expression pattern." (PMID 36584094, 2022). "There was a negative additive interaction between ACE2 G8790A and CYP11B2-344T/C on EH (U3 = − 2.221, P = 0.026, and S = 0.128) and a positive multiplicative interaction between ACE I/D and CYP11B2-344T/C on essential hypertension (P = 0.041)." (PMID 35130889, 2022). "In this study population, the statistically significant difference between participants with and without hypertension in the following RAAS sites: rs4425 and rs4337 in the ACE gene, rs29876 in the ATR gene and rs1912 in the CYP11B2 gene." (PMID 31484569, 2019).
adenoma (64 papers, 2013 to 2026). A neoplasm arising from the epithelium. "Classical PA, defined by a solitary well-circumscribed CYP11B2-positive adenoma, is strongly associated with complete biochemical response and therefore reflects true unilateral disease." (PMID 41066498, 2025). "A finding of CYP11B2-positive adenoma is indicative of cure of primary aldosteronism, whereas smaller CYP11B2-positive nodules associate with poorer results at postoperative evaluation." (PMID 38051154, 2024). "APDH, along with other characterized CYP11B2-positive adrenal cortical lesions including carcinoma, adenoma, nodules, micronodules, are the underlying causes of PA." (PMID 39170743, 2024). "The patient harboring somatic KCNJ5 157-159delITE mutation showed positive staining for CYP11B2 in her adenoma and in an aldosterone-producing micronodule in the adjacent adrenal tissue." (PMID 34440230, 2021). "For these Sanger sequencing-identified mutation carriers, CYP11B2 staining was homogeneous within adenoma." (PMID 34572353, 2021). "Aldosterone-producing adenomas with CTNNB1 mutations have been reported to have higher CYP11B2 mRNA and protein (by immunohistochemistry) expression levels compared to those harboring KCNJ5 mutations." (PMID 29594118, 2018). "The results of mRNA expression from real-time PCR showed that CTNNB1 mutated adenoma had similar density of CYP11B2 expression as WT patients; however, both groups of adenoma had less CYP11B2 expression than those with KCNJ5 mutations (all p < 0.01)." (PMID 28102204, 2017). "The finding of CYP11B2 positive adenoma strongly associated with achieving cure from PA." (PMID 38051154, 2024). "We have followed a customized and targeted gene panel NGS approach which could reach a close 80-90% detection rate of mutations in aldosterone-producing adenomas as a CYP11B2 IHC-guided targeted NGS approach." (PMID 35757409, 2022). "For those 11 cNGS-identified mutation carriers, CYP11B2 staining could be homogeneous or heterogeneous within adenoma." (PMID 34572353, 2021). "Genotype data in this study, as in most preceeding studies, should be interpreted with caution because recent evidence shows that when sequencing is targeted to areas of the adenoma that are positive for CYP11B2 expression, somatic mutations are detected in almost 90% of APAs." (PMID 30654107, 2019). "CXCR4 is highly expressed in the zona glomerulosa and in aldosterone-producing adenomas, and it closely correlates with CYP11B2 (aldosterone synthase) expression." (PMID 41991734, 2026). "Three IHC patterns were identified: CYP11B2-positiveadenomas, mixed CYP11B1/CYP11B2 adenomas, and multiple small CYP11B2-positivenodules." (PMID 41196931, 2025). "There is a negative correlation between the mRNA levels and methylation rates of CYP11B2 in aldosterone-producing adenomas." (PMID 39596027, 2024). "The presence of a CYP11B2-positive adenoma and the use of functional subtyping independently predicted clinical cure of primary aldosteronism." (PMID 38051154, 2024). "Immunohistochemical staining revealed that the left adenoma primarily comprised clear cells expressing CYP11B2, whereas the right adenoma comprised both eosinophilic compact and clear cells expressing CYP11B1." (PMID 36960396, 2023). "The cortisol-producing enzyme cytochrome P450 (CYP) 11B1 was diffusely expressed in the adenoma, but based on staining, the aldosterone synthase CYP11B2 was significantly expressed in the adjacent adrenal cortex." (PMID 38017509, 2023). "In agreement with the previously observed effect in NCI-H295R cells and mouse adrenal fragments, incubation of human adenoma fragments with tacrolimus dramatically impaired K+-dependent stimulation of CYP11B2." (PMID 37310791, 2023). "The pathological report revealed adrenocortical adenoma, the Weiss score was 1, and immunohistochemistry showed weak CYP11B1 expression in the adenoma and positive CYP11B2 expression in an adjacent nodule." (PMID 38017509, 2023).
adenoma (continued). "The mRNA levels of steroidogenic enzymes (including CYP11B1 and CYP17A1) were high in the right adenoma, whereas CYP11B2 was highly expressed in the left adenoma." (PMID 36960396, 2023). "Zona glomerulosa cells, and aldosterone-producing cell clusters in normal adrenal cortex or those affected by aldosterone producing adenoma, can express aldosterone synthase (i.e., CYP11B2), which is responsible for the final step of aldosterone synthesis." (PMID 37509718, 2023). "CYP11B1 and CYP17A1 were highly expressed in the right adenoma and CPAs, whereas CYP11B2 was highly expressed in the left adenoma and APAs compared with other adrenal diseases and nonfunctional adenoma." (PMID 36960396, 2023). "All patients underwent segmental adrenal venous sampling (sAVS) and adrenalectomy, and were pathologically confirmed to have cytochrome P450 11B2 (CYP11B2)-positive aldosterone-producing adenoma according to international histopathology consensus criteria." (PMID 35482752, 2022). "Among 104 patients with adenoma, 91 showed positive CYP11B2 immunostaining in their tumors; whereas 11 patients showing multiple CYP11B2-positive immunostaining tumors were considered as multiple APAs." (PMID 34631800, 2021). "We also revealed that in uPA patients with CYP11B2 positive stained adenomas (true APA), the occurrence of the NGS-identified aldosterone-driver gene mutations were highly indicative of complete clinical success after adrenalectomy." (PMID 34572353, 2021). "The steroid 18-hydroxylase (CYP11B2; aldosterone synthase) IHC staining showed intense density within that compact zona glomerulosa (ZG)-like adenoma." (PMID 34572956, 2021). "The histopathological examination showed a well-defined compact, ZG-like classical adenoma and intense immunoreactivity to CYP11B2 staining." (PMID 34572956, 2021). "The immunohistochemistry staining showed a compact and well demarcated ZG-like adenoma, with intense CYP11B2 expression." (PMID 34572956, 2021). "In this case, the immunohistochemical patterns of HSD3B were similar to those of CYP11B2 in adenoma." (PMID 34440230, 2021). "In the APA harboring KCNJ5 157-159delITE mutation, the immunohistochemistry (IHC) analysis showed a strong immunoreactivity and heterogenous expression for aldosterone synthase (CYP11B2) within that adenoma." (PMID 34440230, 2021). "The CYP11B2 immunohistochemistry staining demonstrated strong immunoreactivity in this classical adenoma." (PMID 34572956, 2021). "Pathology and immunohistochemistry revealed a right adrenal tyrosine hydroxylase–positive PHEO and CYP11B2-positive adenoma." (PMID 34258494, 2021). "In this patient, we performed immunohistochemical analyses for CYP11B2, 3βHSD, and P450c17 and found that he had a right adenoma that autonomously produced aldosterone and a left adenoma that autonomously produced cortisol, consistent with the results of AVS." (PMID 31208392, 2019). "We also analyzed the expression of cortisol-producing CYP11B1 and aldosterone-producing CYP11B2 enzymes in adenoma tissue from 57 patients with aldosterone-producing adenoma, employing immunohistochemistry with digital image analysis." (PMID 28422753, 2017). "Using the mouse monoclonal antibody for CYP11B2 and H-E stain, we extracted the possibility of adenoma for study." (PMID 28415786, 2017). "CYP11B2 expressed diffusely on adenomas harboring CTNNB1 mutations and showed mottled staining on adenomas harboring KCNJ5 mutations." (PMID 28102204, 2017). "Further support to the activation of SF-1 in the rat tumors came from the validation of Cyp11b1 and Cyp11b2 overexpression in independent adenoma samples." (PMID 23756599, 2013). "Furthermore, DNA methylation analysis of the adenoma indicated hypermethylation in the CYP11B2 promoter region." (PMID 39027636, 2024). "Hypomethylation status of the CYP11B2 promoter region is seen in aldosterone-producing adenomas." (PMID 36982850, 2023).